SOHLH2 (spermatogenesis and oogenesis specific basic helix-loop-helix 2)
Description:
Transcription regulator of both male and female germline differentiation. Suppresses genes involved in spermatogonial stem cells maintenance, and induces genes important for spermatogonial differentiation. Coordinates oocyte differentiation without affecting meiosis I (By similarity).
Synonyms: TEB1; FLJ20449; bHLHe81; SPATA28; SOSF2
Tractability: No criterion of Open Targets' tractability assessment is met for any kind of drug.
Gene: Protein-coding gene on chromosome 13 (36,168,217 to 36,214,588, reverse strand). Ensembl gene ENSG00000120669.
Subcellular location: Nucleus; Cytoplasm
Subcellular location (Human Protein Atlas): Vesicles
Gene Ontology:
Molecular function: sequence-specific double-stranded DNA binding; DNA-binding transcription factor activity, RNA polymerase II-specific; protein heterodimerization activity; protein homodimerization activity; DNA-binding transcription factor activity; protein dimerization activity
Biological process: cell differentiation; oocyte differentiation; regulation of transcription by RNA polymerase II; spermatogenesis; regulation of DNA-templated transcription
Cellular component: chromatin; cytoplasm; nucleus
Genetic constraint (gnomAD): Loss-of-function variants: 21 observed, 50.79 expected, observed/expected ratio (o/e) 0.41, 90% interval 0.29 to 0.6. The upper end of that interval is the gene's LOEUF score, 0.6, which puts it in group 2 of 6, group 1 being the genes least tolerant of losing a copy. Missense variants: 408 observed, 520.87 expected, observed/expected ratio (o/e) 0.78, 90% interval 0.72 to 0.85. Synonymous variants: 183 observed, 193.53 expected, observed/expected ratio (o/e) 0.95, 90% interval 0.84 to 1.07.
Homologues: Orthologues: chimpanzee SOHLH2 (97% identical), macaque SOHLH2 (90% identical), rabbit SOHLH2 (72% identical), dog SOHLH2 (72% identical), pig SOHLH2 (71% identical), rat Sohlh2 (54% identical), mouse Sohlh2 (52% identical). Paralogues in human: SOHLH1 (12% identical).
Diseases named in the same sentence as SOHLH2 in open-access papers:
SOHLH2 is named in the same sentence as 23 diseases in open-access papers, as found by Europe PMC text mining. Sharing a sentence is not in itself a finding about the gene and the disease. The quoted sentences say what the papers report.
infertile (4 papers, 2015 to 2024). "Loss of Sohlh1 or Sohlh2 causes infertility by disrupting spermatogonial differentiation into spermatocytes or ovarian follicle differentiation from primordial to growing follicles." (PMID 26375665, 2015). "Sohlh2 is of particular interest as it has been described to be required for oocyte growth, and Sohlh2−/− females were found to be infertile." (PMID 29661911, 2018). "Studies in mouse indicate that NOBOX, SOHLH1/SOHLH2 and LHX8 are co-expressed and cross-regulate each other, either directly or indirectly, thus controlling oocyte development during early follicular progression and therefore their mis-regulation leads to infertility." (PMID 39391877, 2024).
ovarian carcinoma (4 papers, 2016 to 2022). A malignant neoplasm originating from the surface ovarian epithelium. "Sohlh2 reduction shows strong associations with the metastasis and overall survival of ovarian cancer patients." (PMID 27384482, 2016). "Among them, Sohlh2 was demonstrated to be an important inhibitor of ovarian cancer cell proliferation and metastasis by repressing the MMP9 expression." (PMID 35187167, 2022). "We have previously reported that Sohlh2 is a new tumor suppressor gene and is downregulated in ovarian cancer and breast cancer." (PMID 35127476, 2021). "We have previously reported that Sohlh2 plays an antitumor role in breast cancer and ovarian cancer." (PMID 35127476, 2021). "In females, too, crucial roles of SOHLH2 have been discovered, for example in the etiology of human premature ovarian failure and in the context of ovarian cancer." (PMID 32164318, 2020).
breast carcinoma (3 papers, 2016 to 2022). "Sohlh2 mRNA and protein were lowly expressed in human breast cancer cell lines, especially in MDA-MB-231 cells, compared with those in HBL-100 and MCF-10a cells." (PMID 27384482, 2016). "Sohlh2 also suppressed breast cancer cell proliferation through Wnt signaling." (PMID 35187167, 2022). "Sohlh2 overexpression also repressed the metastasis of breast cancer cells in vivo." (PMID 27384482, 2016). "Sohlh2 expression was examined in 77 cases of primary human invasive ductal breast cancer specimens, 16 cases intraductal carcinoma in situ, and 25 cases adjacent tissues of breast cancer by immunohistochemitry (IHC) assay." (PMID 27384482, 2016).
colon cancer (2 papers, 2016 to 2025). "Sohlh2 suppressed the proliferation, migration, and invasion of ovarian, breast and colon cancer cells through transcriptional regulation of P21, Cyclin D1 and APC." (PMID 40418209, 2025).
premature ovarian failure (2 papers, 2015 to 2020). "Novel variants in the Sohlh2 gene were also found in women with premature ovarian failure (POF) of both Chinese and Serbian." (PMID 26375665, 2015).
pulmonary fibrosis (2 papers, 2023 to 2025). Chronic progressive interstitial lung disorder characterized by the replacement of the lung tissue by connective tissue, leading to progressive dyspnea, respiratory failure, or right heart failure. "Taken together, these results suggest that NAC reduces the oxidative stress of AECIIs and pulmonary fibrosis caused by Sohlh2." (PMID 37875506, 2023). "Using AECII specific Sohlh2 CKI mouse model, we confirmed that Sohlh2 overexpression caused mitochondrial damage in AECIIs and spontaneous lung fibrosis, and Sohlh2 in AECIIs also largely enhanced HFD-driven oxidative stress, fibrotic remodeling, inflammation, and cell death." (PMID 37875506, 2023). "Another study suggested that Sohlh2 can promote pulmonary fibrosis by transcriptional repression of the p62/Keap1/Nrf2 mediated anti-oxidative signaling pathway." (PMID 40170095, 2025). "In the present study, the mechanisms associated with how Sohlh2 induced age-related or HFD-induced redox imbalance, and accelerated lung fibrosis, were investigated at a multi-system level." (PMID 37875506, 2023). "The analyses above clearly elucidate that Sohlh2 aggravates pulmonary fibrosis induced by HFD." (PMID 37875506, 2023). "To further confirm the mechanism of Sohlh2 in the regulation of AECII oxidative stress during the development of pulmonary fibrosis, we examined the effect of Sohlh2 on regulating the p62/Keap1/Nrf2 signaling pathway in the lung tissues of 8 M and HFD-fed mice." (PMID 37875506, 2023). "Moreover, we found that p62 was a direct target gene of Sohlh2, and mediated the effects of Sohlh2 on oxidative stress damage and lung fibrosis." (PMID 37875506, 2023). "Our study provided proof that targeting Sohlh2 may prevent age-related and stress-induced pulmonary fibrosis." (PMID 37875506, 2023). "To explore the role of Sohlh2 in pulmonary fibrosis induced by metabolic stress, we fed 8-week-old Sohlh2 KI mice with HFD containing 60% fat by kilocalories for 8 weeks and assessed their lung morphology, inflammatory responses, and collagen deposition after HFD treatment." (PMID 37875506, 2023). "Our study demonstrated that Sohlh2 overexpression inhibited the activation of the p62/Keap1/Nrf2 signaling pathway by repressing p62 transcription to induce oxidative stress in AECIIs, which led to severe pulmonary fibrosis." (PMID 37875506, 2023). "p62 mediated the effects of Sohlh2 on ROS production and the development of pulmonary fibrosis." (PMID 37875506, 2023). "Our findings provided evidence that Sohlh2 may be a therapeutic target in lung fibrosis." (PMID 37875506, 2023). "Sohlh2 overexpression led to age-related pulmonary fibrosis and augmented HFD-induced pulmonary fibrosis via induction of ROS generation." (PMID 37875506, 2023). "Using a type II AEC-specific Sohlh2 conditional knock-in (CKI) mouse model, we found that Sohlh2, a basic HLH transcription factor, accelerated age-related pulmonary fibrosis." (PMID 37875506, 2023). "Sohlh2 KI mice developed age-related progressive lung fibrosis, Masson’s trichrome staining showed accelerated collagen deposition in the Sohlh2 KI group, while there were indistinguishable between the two groups at the age of 2 months." (PMID 37875506, 2023). "Here we uncovered a critical role for Sohlh2 in age-related and HFD-induced pulmonary fibrosis." (PMID 37875506, 2023). "The Control and Sohlh2 KI mice were fed with HFD, meanwhile treated with or without 100 μL NAC (30 mg/mL) for 8 weeks to evaluate whether scavenging ROS attenuates the occurrence and progression of pulmonary fibrosis." (PMID 37875506, 2023).
Azoospermia (1 paper, 2020). Absence of any measurable level of sperm,whereby spermatozoa cannot be observed even after centrifugation of the semen pellet. "At the genetic level, mutations in SOHLH1 gene have already been associated with non-obstructive azoospermia as well as genetic variants in SOHLH1 and SOHLH2 with non-obstructive azoospermia risk in Chinese men." (PMID 32164318, 2020).
carcinoma in situ (1 paper, 2016). "Sohlh2 expression was observed in all (100%) adjacent tissues, all (100%) intraductal carcinoma in situ, and in 47 of 77 (61.04%) of invasive ductal carcinoma." (PMID 27384482, 2016).
metastatic tumors (1 paper, 2016). "Sohlh2 overexpression dramatically decreased the number of metastatic tumors in the lungs." (PMID 27384482, 2016).
ovarian failure (1 paper, 2015). "Previously, we discovered that global knockouts of germ cell-specific transcriptional co-regulators Sohlh1, Sohlh2, Lhx8, and Nobox, cause rapid oocyte loss and ovarian failure." (PMID 26076587, 2015).
renal cell carcinoma (1 paper, 2021). "To clarify the role of Sohlh2 in the occurrence and development of renal cell carcinoma, we constructed stably transfected human renal cell carcinoma cell lines with Sohlh2 overexpression and Sohlh2 knockdown, separately." (PMID 35127476, 2021). "Our study suggests that Sohlh2 and DNMT3a/Klotho can be used as potential targets for the clinical treatment of renal cell carcinoma." (PMID 35127476, 2021). "Sohlh2 functions as a tumor suppressor gene in renal cell carcinoma by demethylation of Klotho via DNMT3a." (PMID 35127476, 2021). "In renal cell carcinoma, Sohlh2 was positively correlated with Klotho and negatively correlated with DNMT3a." (PMID 35127476, 2021). "Our results showed that Sohlh2 was downregulated in renal cell carcinoma, and its expression level was negatively correlated with tumor staging." (PMID 35127476, 2021). "Sohlh2 correlated with Klotho positively and with DNMT3a negatively in renal cell carcinoma." (PMID 35127476, 2021). "Finally, we collected 40 resected renal cell carcinoma samples to study the relevance between Sohlh2, DNMT3a, and Klotho by immunohistochemistry." (PMID 35127476, 2021). "First, we studied the effects of Sohlh2 on proliferation, migration, invasion, and epithelial–mesenchymal transition (EMT) of renal cell carcinoma cells in vitro and in vivo." (PMID 35127476, 2021). "Both in vitro and in vivo experiments confirmed that Sohlh2 overexpression inhibited the proliferation, migration, invasion, metastasis, and EMT of renal cell carcinoma." (PMID 35127476, 2021). "Sohlh2 is a newly discovered tumor suppressor gene playing inhibitory roles in a variety of tumors, but its role in renal cell carcinoma has not been reported." (PMID 35127476, 2021).
cancer (5 papers, 2007 to 2026). A tumor composed of atypical neoplastic, often pleomorphic cells that invade other tissues. "Mechanistically, SOHLH2 transcriptionally activated the expression of RAD54L, thereby promoting HR repair and the survival of cancer cells in response to radiation." (PMID 41535248, 2026). "Two HIOTs of RGN11153 are found in cancer genes ZFHX3 (exon) and SOHLH2 (intron)." (PMID 35831290, 2022). "As in the cancer cell lines, we observed promoter hypomethylation in the primary tumors; the frequency of hypomethylation was 5% (1/20) for ANKRD30A, 20% (4/20) for FLJ40201, 0% (0/20) for INSL6, 30% (6/20) for SOHLH2, 20% (4/20) for FTMT, 25% (5/20) for C12orf12, and 30% (6/20) for DPPA5." (PMID 17967063, 2007).
tumor (5 papers, 2016 to 2026). "Our research unveiled that the expression levels of SOHLH2 increased in NSCLC compared with adjacent non-tumor tissues." (PMID 41535248, 2026). "Sohlh1 and Sohlh2 are both members of the bhlh family of transcription factors and are novel tumour suppressors." (PMID 40418209, 2025). "In an orthotopic xenograft model of TNBC, we revealed a metastasis-promoting function for macrophage-specific Sohlh2 KI mice in vivo, which was mediated in part by convening Sohlh2-dependent M2 polarization of macrophages in the primary tumor." (PMID 38123542, 2023). "The tumor growth of Sohlh2 KI xenografts was markedly promoted as demonstrated by the increased volume and weight compared with the Con group." (PMID 38123542, 2023). "The results showed that Sohlh2 overexpression inhibited RCC tumor growth, while Sohlh2 knockdown had the opposite effects (p < 0.05)." (PMID 35127476, 2021). "Sohlh2 significantly inhibits the proliferation, migration, invasion, and metastasis of tumor cells." (PMID 35127476, 2021). "In addition, our results also suggested that Sohlh2 might upregulate Klotho’s expression level by downregulating the expression of DNMT3a and thus functioned as a tumor suppressor in human RCC." (PMID 35127476, 2021). "After exploring the effect of Sohlh2 on RCC cells in vitro, we continued to detect the role of Sohlh2 in RCC through subcutaneous implantation and tail vein injection of RCC cells in nude mice to assess whether Sohlh2 affects tumor growth and metastasis in vivo." (PMID 35127476, 2021).
SOHLH2 also shares sentences with these, for which no sentence is quoted: gastric cancer (2 papers); gestational diabetes (1); glioma (1); invasive breast carcinoma (1); invasive ductal carcinoma (1); lymph node metastasis (1); multiple myeloma (1); non-small cell lung carcinoma (1); renal carcinoma (1); triple-negative breast carcinoma (1).